MAP2K1 (mitogen-activated protein kinase kinase 1)
Diseases named in the same sentence as MAP2K1 in open-access papers (continued):
Sharing a sentence is not in itself a finding about the gene and the disease.
melorheostosis (continued). "We present genetic, functional and histological data supporting the enhancement of MEK1 activity predicted by the location of the mutations and the causative role of the MAP2K1 mutations in melorheostosis." (PMID 29643386, 2018). "Our data show that the MAP2K1 oncogene is important in human bone formation and implicate MEK1 inhibition as a potential treatment avenue for melorheostosis." (PMID 29643386, 2018). "Cases of melorheostosis without the MAP2K1 mutation lack the candle wax sign and do not have increased osteoblast/osteoclast counts when examined histologically." (PMID 39945784, 2025). "However, the clinical benefit with antiresorptives is counterintuitive given the enhanced osteoblast growth seen in MAP2K1‐positive melorheostosis." (PMID 31485554, 2019). "The occurrence of the mutations in a MEK1 “hot spot,” and the evidence of enhanced MEK1-ERK1/2 signaling in melorheostotic bone and osteoblasts, strongly support MAP2K1 somatic mutations as causing about half of cases of sporadic melorheostosis." (PMID 29643386, 2018). "Using whole exome sequencing, we identify somatic mosaic MAP2K1 mutations in affected, but not unaffected, bone of eight unrelated patients with melorheostosis." (PMID 29643386, 2018). "We identified mutations in MAP2K1 in the affected, but not unaffected, bone of 8 of 15 patients diagnosed clinically and radiologically with melorheostosis." (PMID 29643386, 2018). "While there is a reported quantitative difference in the counts of osteoblasts/osteoclasts between MAP2K1 mutation positive and negative cases of melorheostosis, there are other features that may be useful in aiding the diagnosis of melorheostosis histologically." (PMID 39945784, 2025).
arteriovenous malformation (10 papers, 2018 to 2024). "Somatic activating MAP2K1 mutations in endothelial cells (ECs) cause extracranial arteriovenous malformation (AVM)." (PMID 37422456, 2023). "The mutation of MAP2K1 is considered the most common cause of extracranial arteriovenous malformations." (PMID 33362847, 2020). "Study of extracranial arteriovenous malformations revealed point mutations and, rarely, in-frame deletions of MAP2K1." (PMID 32483240, 2020). "Within 4 of 11 (36%) individuals with fast-flow lesions (arteriovenous malformations [AVM]) we identified somatic variants in KRAS and MAP2K1 with VAFs ranging from 1.27% to 9.98%." (PMID 39669602, 2024). "The etiology of CCT is associated with a mutation of the GNAQ gene, the RASA1 gene, or the MAP2K1 gene.Mutations of the latter two genes are associated with the coexistence of CCT and arteriovenous malformations (AVMs)." (PMID 36013378, 2022). "Besides, MAP2K1 mutation activates RAS/MAPK signaling in endothelial cells and is associated with extracranial arteriovenous malformation." (PMID 38431286, 2024).
cutaneous melanoma (10 papers, 2017 to 2025). A primary melanoma arising from atypical melanocytes in the skin. "The reported frequencies of mutations in cutaneous melanoma are 37–60% in BRAF, 13–25% in NRAS, 12% in NF1, 6–7% in MAP2K1, and 2–8% in KIT." (PMID 41295253, 2025). "The most common allelic variants (AV) in cutaneous melanoma tissues include BRAF, neuroblastoma RAS viral oncogene homolog (NRAS), mitogen-activated protein kinase kinase 1 (MAP2K1), and proto-oncogene c-KIT (KIT)." (PMID 35205608, 2022).
histiocytic neoplasm (10 papers, 2018 to 2026). Histiocytic tumors are a heterogeneous group of tumors and tumorlike masses commonly associated with histologically identical extracranial lesions. "MAP2K1 activating mutations are known in the literature to play a critical role in histiocytic neoplasms, where in individual cases, responses to a cobimetinib therapy have been described." (PMID 36013219, 2022). "The lower response exhibited by patients with this subtype of mutation is consistent with previous studies, although further studies are needed to confirm the role of MAP2K1 class III mutations as a driver of resistance to MEK inhibitors in patients with histiocytic neoplasms." (PMID 41035796, 2025). "KRAS mutations, along with MAP2K1, are frequently found in RDD and likely contribute to its role as a clonal histiocytic neoplasm." (PMID 41552389, 2026). "MAP2K1, also known as MEK1, plays a critical role in inhibiting the progression of histiocytic neoplasms." (PMID 34975891, 2021). "This review covers the current understanding of histiocytic neoplasms, molecular pathophysiology, with a particular focus on mutations in genes such as BRAF, MAP2K1, and the PI3K-AKT signaling pathways, and evolving treatment strategies, especially focusing on LCH, ECD, RDD, and JXG." (PMID 38963520, 2024).
neurofibromatosis type 1 (9 papers, 2011 to 2025). A clinically heterogeneous, neurocutaneous genetic disorder characterized by cafe-au-lait spots, iris Lisch nodules, axillary and inguinal freckling, and multiple neurofibromas. "Seven genes (PTPN11, SOS1,KRAS, RAF1, BRAF,SHOC2 and MEK1, alias MAP2K1) have beencausally related to NS and closely related conditions (including LEOPARDsyndrome) and clinically related disorders (e.g. neurofibromatosis type 1)." (PMID 21526175, 2011).
metastatic tumors (8 papers, 2008 to 2025). "The MAPK pathway showed mutations in the BRAF, KRAS, and MAP2K1 genes in three brain metastatic tumors that were not present in their breast primary tumors." (PMID 36507516, 2022). "Collectively, our analysis of single cell sequencing data suggested that the TME of primary tumor of NSCLC are enormously immunosuppressive than the metastatic tumor and are populated by high expression levels of EGFR/MAP2K1/MTOR/TEAD1/YAP1 within tumor microenvironment of NSCLC." (PMID 35655775, 2022).
esophageal cancer (7 papers, 2017 to 2025). A primary or metastatic malignant neoplasm involving the esophagus. "It prevents its expression by binding with the target gene MAP2K1 (MEK1), thus affecting the proliferation and metastasis of esophageal cancer cells." (PMID 35468097, 2022).
myocardial infarction (7 papers, 2008 to 2024). Gross necrosis of the myocardium, as a result of interruption of the blood supply to the area, as in coronary thrombosis. "When subsetting the statistical tests by MAF range, BTH uncovers six associations, including a locus regulating variance of the gene DIS3L, recently identified as a possible risk factor for myocardial infarction, and a locus regulating the variance of the gene MAP2K1, involved in cardiac signaling." (PMID 29982387, 2019).
Cognitive impairment (6 papers, 2018 to 2026). Abnormal cognition is characterized by deficits in thinking, reasoning, or remembering. "Given that AF has been shown to alleviate cognitive disorders and MAP2K1 regulates the HIF‐1α signaling pathway, while hyperuricemia activates the ERK pathway influencing HIF‐1α, we investigated whether AF improves HUA‐CI by modulating the HIF‐1 signaling pathway." (PMID 41561638, 2026).
COVID-19 (6 papers, 2022 to 2026). A disease caused by infection with severe acute respiratory syndrome coronavirus 2. "A decrease in the expression of the following genes was also observed in COVID-19-positive patients: RAPGEF1 (p = 0.0091), MAP2K1 (p = 0.038), CEBPB (p = 3.3 × 10−6), STAT6 (p = 0.041), JUN (p = 1.4 × 10−8), PRKACA (p = 0.021), and AKT1 (p = 1.3 × 10−6)." (PMID 36298734, 2022).
hairy cell leukemia (6 papers, 2017 to 2026). Hairy cell leukemia (HCL) is a rare type of leukemia in which abnormal B-lymphocytes are present in the bone marrow, spleen and peripheral blood. "Especially, MAP2K1 mutations lead to poorer prognosis in hairy cell leukemia patients and must be confirmed in a cohort with a greater number of patients." (PMID 35454811, 2022). "Hairy cell leukemia is virtually universally characterized by the BRAFV600E hotspot mutation, with the exception of cases using the IGHV4-34 family, which may show MAP2K1 mutations and are similar to hairy cell leukemia variant." (PMID 37747559, 2024). "A similar mutual exclusivity of BRAF and MAP2K1 mutations has also been reported in other neoplasms, including hairy cell leukemia (HCL) and various epithelial malignancies." (PMID 32483240, 2020).
heart failure (6 papers, 2021 to 2025). Inability of the heart to pump blood at an adequate rate to meet tissue metabolic requirements. "Dysregulation of MAP2K1 has been associated with various CVDs, including heart failure and arrhythmias." (PMID 39069811, 2025). "It has been shown that the insulin signaling pathway is inactivated during the development of heart failure, and MAP2K1 is a key downstream gene of the insulin signaling pathway." (PMID 37234159, 2023). "It has been previously demonstrated that MYC, MAP2K1, and STAT3 all have a critical role in the development of heart failure." (PMID 37234159, 2023). "By using Cytoscape software (Version: 3.10.2) in conjunction with MCC algorithms of the CytoHubba plugin, we identified the top 5 hub genes within the network (IL1B, NFKB1, MAP2K1, PRKACA, and HSP90AA1), suggesting that these genes are potential targets for EMPA and MET in heart failure therapy." (PMID 40364820, 2025). "The study also indicates that the three CSA-signature genes (MYC, MAP2K1, and STAT3) may not only act as potential biomarkers for heart failure but also be potential targets for future research in the development of new treatment strategies for heart failure." (PMID 37234159, 2023).
breast tumor (5 papers, 2017 to 2021). "Basal human breast tumours also carried protein expression outliers in IDH1, EGFR and MAP2K1." (PMID 28348404, 2017).
Costello syndrome (5 papers, 2007 to 2023). "The remaining genes involved were RAF1 (three patients, all with Costello syndrome suspicion), RIT1 (two patients), BRAF (one patient), MAP2K1 (three patients), MAP2K2 (two patients), PTPN11 (two patients), SOS1 (one patient), and SHOC2 (three patients, two of them with Costello syndrome suspicion)." (PMID 37568403, 2023).
epilepsy (5 papers, 2023 to 2024). A brain disorder characterized by episodes of abnormally increased neuronal discharge resulting in transient episodes of sensory or motor neurological dysfunction, or psychic dysfunction. "The results indicated that pulmonary valve stenosis, curly/sparse hair, and epilepsy were less likely to occur in Chinese CFC patients with BRAF variants, whereas curly/sparse hair and hypotonia were rare in Chinese patients with MAP2K1/2 variants." (PMID 37697378, 2023).
esophageal squamous cell carcinoma (5 papers, 2019 to 2025). Esophageal squamous cell carcinoma (ESCC) is a type of esophageal carcinoma (EC) that can affect any part of the esophagus, but is usually located in the upper or middle third. "In particular, miR-181a-5p inhibits cell migration, invasion and proliferation by repressing the ERK-matrix metalloprotease (MMP) pathway via targeting the Dual specificity mitogen-activated protein kinase kinase 1 (MAP2K1/MEK1) as shown in esophageal squamous cell carcinoma." (PMID 39412616, 2025).
influenza (5 papers, 2013 to 2025). An acute viral infection of the respiratory tract, occurring in isolated cases, in epidemics, or in pandemics; it is caused by serologically different strains of viruses (influenzaviruses) designated A, B, and C, has a 3-day incubation period, and usually lasts for 3 to 10 days. "Other downregulated genes after 2-days were pik3r5, akt3a, nfkbiab, hras, mapk14a in hepatitis, pik3r5, akt3a, il1b, il12a, raf1b, map2k1 in influenza and pik3r5, akt3a, nfkbiab, il1b, il12a in measles." (PMID 24069208, 2013).
vascular malformation (5 papers, 2019 to 2025). A non-neoplastic disorder that is the result of defects of vascular morphogenesis. "The specific mutations of MAP2K1(K57N), MAP2K1(Q58del) and BRAF(V600E) show strong activation on ERK, which may account for significant activation of the MAPK pathway in those sporadic vascular malformations." (PMID 31067686, 2019).
B-cell lymphoma (4 papers, 2015 to 2022). "The canonical pathway suggested to be affected for Bx T-cell lymphomas reflect the recurrent mutations in PTEN and MAP2K1; these two genes are mutated in 38% of all Bx T-cell lymphomas and not in a single Gr T-cell lymphoma or any of the B-cell lymphomas in this study." (PMID 26377837, 2015).
cardiomyopathy (4 papers, 2018 to 2023). A disease of the heart muscle or myocardium proper. "The components of the MAPK pathway, such as MAP2K1 through MAPK3, as well as the Ras-related proteins, RAP1A, RAP1B, and M-Ras, had a median 2.6-fold (IQR, 2.0-fold to 15.5-fold) upregulation among patients with SARS-CoV-2 infection compared with patients with noninflammatory cardiomyopathy." (PMID 34910083, 2022).
oral cancer (4 papers, 2015 to 2023). "This study permitted the proposal of 8 salivary biomarkers for oral cancer in patients previously infected with HPV (RPRD2, PSCA, MCM2, CDKN2A, BAK1, HSPA1A, TANK, MAP2K1)." (PMID 37599356, 2023).
Rosai-Dorfman disease (4 papers, 2018 to 2026). "The biopsy showed enriched IgG-4 peri-renal Rosai Dorfman disease with MAP2K1 mutation, although peri-renal infiltration is highly suggestive of Erdheim-Chester disease." (PMID 34222286, 2021). "There were two Rosai-Dorfman disease (RDD) patients carry BRAF and MAP2K1 mutation simultaneously." (PMID 36536400, 2022).
diffuse large B-cell lymphoma (3 papers, 2020 to 2022). "It has also been shown that miRNA-101 affects the ERK/MAPK pathway by targeting MAP2K1 to regulate proliferation and apoptosis in diffuse large B-cell lymphoma." (PMID 36203485, 2022).
follicular lymphoma (3 papers, 2017 to 2024). Follicular lymphoma is a form of non-Hodgkin lymphoma characterized by a proliferation of B cells whose nodular structure of follicular architecture is preserved. "MAP2K1 mutations resulting in ERK pathway activation were found to be the most frequent aberrations in paediatric follicular lymphoma." (PMID 39284897, 2024).
meningioma (3 papers, 2013 to 2025). A generally slow growing tumor attached to the dura mater. "The T cells in meningioma showed five additional drug-target kinases that were significantly increased in expression compared to VS (CSF1R, LYN, ABL, MAP2K1, and BRAF), whereas VS had only one drug-target kinase, KDR." (PMID 41437121, 2025).
myocardial ischemia (3 papers, 2014 to 2024). A disorder of cardiac function caused by insufficient blood flow to the muscle tissue of the heart. "In a myocardial ischemia-reperfusion model, the activation of ERK1/2 has been found to reduce apoptosis caused by reperfusion injury, indicating that the MAP2K1 signaling pathway may provide cardioprotective effects." (PMID 38347953, 2024).
nevus (3 papers, 2020 to 2025). Nevus (or naevus, plural nevi or naevi, from nævus, Latin for "birthmark") is the medical term for sharply circumscribed[1] and chronic lesions of the skin or mucosa. "A novel MAP2K1 mutation was detected in CMN for the first time, which may suggest that the MAP2K1 mutation contributes to the occurrence and development of nevus, expanding our knowledge of the genetics of CMN." (PMID 32847629, 2020).
Obesity (3 papers, 2021 to 2024). Accumulation of substantial excess body fat. "The results revealed that 18 of the DMR genes were associated with addiction and obesity (ADCY3; ADCY9; ATF4; CDK5R1; CHRNB2; GABRD; GABRG3; GNB1; GNB3; GRK5; HDAC4; HDAC9; MAP2K1; PDE11A; PDE2A; PDE3A; PPP1CA; SLC6A3)." (PMID 34389046, 2021).
osteoporosis (3 papers, 2020 to 2022). A condition of reduced bone mass, with decreased cortical thickness and a decrease in the number and size of the trabeculae of cancellous bone (but normal chemical composition), resulting in increased fracture incidence. "This suggested that the related target molecules had an important role in GCK-treated osteoporosis, especially for the targets STAT3, PIK3R1, VEGFA, JAK2 and MAP2K1." (PMID 36430397, 2022).
Papillary Thyroid Cancer (3 papers, 2014 to 2022). "Clinico-pathological characteristics of MAP2K1 mutant papillary thyroid cancer case." (PMID 34046359, 2021).
psoriasis (3 papers, 2013 to 2025). An autoimmune condition characterized by red, well-delineated plaques with silvery scales that are usually on the extensor surfaces and scalp. "Other reported manifestations included psoriasis and celiac disease, each identified in two individuals (3.6%; one with a BRAF and one with a MAP2K1 mutations, respectively)." (PMID 40692796, 2025).
sarcoma (3 papers, 2015 to 2024). A usually aggressive malignant neoplasm of the soft tissue or bone. "The MAP2K1 E203K mutation was detected in the pre- and post-therapeutic specimens of an undifferentiated (pleomorphic) sarcoma." (PMID 34356494, 2021). "Some MAP2K1 mutations have already demonstrated druggability within sarcoma patients." (PMID 34356494, 2021). "In addition, two potentially druggable mutations, a MAP2K1 missense mutation (E203K) and a BRAF missense mutation (V600E), were traceable in two undifferentiated (pleomorphic) sarcoma patients (11%; 2/18)." (PMID 34356494, 2021). "The rat sarcoma (RAS) pathway was also markedly deregulated and marker genes for cell proliferation were found to be downregulated (e.g., FGF11, PKCA, MAP2K1)." (PMID 38375032, 2024). "Besides two non-synonymous mutations in MAP2K1 (p.Q203K) and BRAF (p.V600E), which both occurred in pleomorphic (undifferentiated) sarcomas (P06, P11), no further mutations could be detected with the OFA." (PMID 34356494, 2021).
cataract (2 papers, 2017 to 2022). Partial or complete opacity of the crystalline lens of one or both eyes that decreases visual acuity and eventually results in blindness. "Transgenic mice that express a constitutively active mutant of Mitogen-activated protein kinase kinase 1 (MEK1) [MEK1(E)] under the control of the αA-crystallin promoter develop macrophthalmia and severe cataracts with major histological abnormalities of the lens that are followed by lens rupture." (PMID 36171977, 2022).
colon adenocarcinoma (2 papers, 2008 to 2020). "Case reports of MEK inhibitory therapy for patient with LCH with MAP2K1 p.E102_103del alteration showed lasting clinical improvement of lesions, while a case of colonic adenocarcinoma with the same deletion showed progression on MEK and ERK inhibitory therapy." (PMID 32483240, 2020).
developmental delay (2 papers, 2016 to 2022). "Except for patient CC4C (MAP2K1 damaging variant), in whom some developmental delay features had already been observed, none of the CDD patients showed signs of the disorders attributed to the genes in which they had damaging de novo variants." (PMID 27955658, 2016).
Erdheim-Chester disease (2 papers, 2021 to 2025). "The first patient was diagnosed with Erdheim-Chester disease (ECD) and exhibited evidence of a MAP2K1 mutation, concomitant with chronic myelomonocytic leukemia." (PMID 40131415, 2025).
ganglioglioma (2 papers, 2014 to 2018). A well differentiated, slow growing neuroepithelial neoplasm composed of neoplastic, mature ganglion cells and neoplastic glial cells. "Our recent genetic analysis revealed that MVNTs harbor frequent MAP2K1 exon 2 mutations or small in-frame deletions, as well as BRAF mutations other than V600E; however, MAP kinase pathway activation in gangliogliomas appears to occur independently of MAP2K1 alterations." (PMID 29880043, 2018).